MTOR (mechanistic target of rapamycin kinase)
Diseases named in the same sentence as MTOR in open-access papers (continued):
Sharing a sentence is not in itself a finding about the gene and the disease.
lung cancer (continued). "Recently, we also discovered that combinatorial treatment with CAP and low-dose RSL3 could provoke ferroptosis via promoting xCT lysosomal degradation through ROS/AMPK/mTOR axis in lung cancer cells." (PMID 41145470, 2025). "Building on our group's previous studies, gracillin has been demonstrated to induce G1-phase cell cycle arrest in A549 lung cancer cells and promote apoptosis by regulating Bcl-2 family protein 28, as well as activate autophagy by inhibiting the mTOR signaling pathway." (PMID 40740238, 2025). "TIPE3 enhances the progression of lung cancer by activating Akt/mTOR, NF-κB, and STAT-3 signaling." (PMID 40280943, 2025). "In cases of lung cancer, IL-7R, mTOR, and tumor stage are important predictors of prognosis." (PMID 39650649, 2024). "It was further revealed that excessive activation of the PI3K/AKT/mTOR signaling pathway could enhance ferroptosis resistance in lung cancer cells, and this was achieved by inducing the expression of SREBP1/SCD1." (PMID 38383297, 2024). "Therefore, all acquired data highlight the essential role of the PI3K/Akt/mTOR pathway in lung cancer progression." (PMID 38203787, 2024). "It has been shown that rapamycin could improve the radiosensitivity of lung cancer cells by suppressing mTOR and improving the radiosensitivity of human glioma stem cells." (PMID 38965615, 2024). "Interestingly, activation of autophagy using the mTOR inhibitor rapamycin reduced PD-L1 expression in lung cancer cells in vitro and in vivo, while activation of mTOR increased PD-L1 expression." (PMID 38467935, 2024). "For example, MTOR is a well-characterized oncogene in several cancers (including cancers of the lung) and its activation promotes cell proliferation, migration, and invasion, thus necessitating pharmacological MTOR inhibition to prevent this uncontrolled growth." (PMID 39510184, 2024). "Additionally, bee venom has been reported to trigger autophagy-induced apoptosis in human lung cancer cells via the mTOR signaling pathway, highlighting its ability to modulate key cellular pathways involved in apoptosis regulation." (PMID 39203027, 2024). "Similarly, a study on lung cancer showed that baicalin can inactivate the AKT/mTOR pathway and promote apoptosis." (PMID 39584140, 2024). "PD-L1 expression is regulated via mTOR signaling in a mouse model of lung cancer." (PMID 38791040, 2024). "Additionally, mTOR activation through an Akt-independent pathway was involved in collagen type I-induced EGFR-TKI resistance in lung cancer cells." (PMID 38397056, 2024). "Surprisingly, FRMD6 bound and activated mTOR in lung cancer, suggesting its tumor promoting role." (PMID 38926528, 2024). "Additionally, β-Elemene can activate the AMPK pathway and inhibit the MAPK/ERK and AKT/mTOR pathways, resulting in the apoptosis of lung cancer cells." (PMID 39584140, 2024). "Notably, resistance to cisplatin has been reported to be associated with the induction of Akt expression in colon cancer, and Akt/mTOR pathway inhibition reduced cisplatin resistance in ovarian and lung cancer cells." (PMID 38399413, 2024). "Additionally, activation of Maf1, a master repressor of Pol III-dependent transcription and mechanistic target of rapamycin (mTOR) downstream effector, alleviates ionizing radiation-induced UPRmt in lung cancer cells." (PMID 39261452, 2024). "Similarly, the suppression of mTOR signaling has been found to reverse EMT and decrease the CSC phenotype in lung cancer cells, as mTOR is a downstream target of Akt." (PMID 38672078, 2024). "Consequently, AF is being investigated in combination with the mTOR inhibitor Sirolimus in lung cancer (NCT01737502) and ovarian cancer (NCT03456700)." (PMID 38515178, 2024). "Therefore, in this study, we confirmed that BQZC, one the one hand, activated the mTOR–BMF–Bax signaling pathway to promote lung cancer cell apoptosis, and on the other, induced autophagy by the AMPK–ULK1 signaling pathway to resist excessive apoptosis." (PMID 39598428, 2024).
lung cancer (continued). "Hence, senolytics that clear senescent cells or mTOR inhibitors that hinder PI3K/mTOR pathway activation can play a therapeutic role in lung cancer patients, including those with COPD." (PMID 39161800, 2024). "Furthermore, the dual mTOR inhibitor, sapanisertib (MLN0128), was tested in a phase II clinical trial for patients with lung cancer, which is at stage IV or recurrent due to mutation in multiple genes related to cancer growth." (PMID 39349424, 2024). "In specific, when two human lung cancer cell lines, A549 and PC-9, were treated with curcumin, a dose-dependent decrease in the expression of Akt and mTOR was observed as a result of the inhibition of hepatocyte growth factor (HGF) and its downstream effector c-Met." (PMID 38672636, 2024). "Therefore, BZW2 overexpression suggests that it is an oncogene in lung cancer related to the phosphorylation of the components of the AKT/mTOR pathway." (PMID 36661515, 2023). "To explore the effect of pharmacological VC on mTOR pathway activation, we treated lung cancer cells (H1299 and A549) with different concentrations of VC for 2 hours and examined the activation status of mTORC1 by assessing the levels of S6K, S6, and 4EBP1 phosphorylation." (PMID 36787291, 2023). "Their analysis showed that the mTOR inhibitor MLN0128 could suppress tumor growth and glycolysis in genetically engineered mouse models (GEMMs) of lung cancer with KRAS and LKB1 co-mutations, as shown by reduced 18F-FDG consumption." (PMID 37190124, 2023). "Compared with normal lung tissue, the expression of piR-55490 was decreased in lung cancer tissue, and inhibition of piR-55490 could promote the proliferation of lung cancer cells by inhibiting the activation of the mTOR pathway in lung cancer cells." (PMID 37503320, 2023). "Researchers have found that the radiation-induced upregulation of exosomes containing miR-208A in lung cancer patients promotes cell proliferation by targeting p21 and the corresponding activation of the AKT/mTOR pathway in lung cancer cells, leading to radiation resistance." (PMID 37322433, 2023). "Furthermore, studies have also shown the use of SSTR2 and dopamine receptor 2 in combination with mTOR inhibitor in lung cancer cells NCI-H727." (PMID 38203605, 2023). "The complex of TF and VIIa, as well as the binding of epidermal growth factor to its receptor in cancer cells present in lung cancer, leads to the activation of the mTOR pathway, and the mTOR pathway leads to an increase in the expression of TF in lung cancer and glioblastoma." (PMID 37280670, 2023). "More recently, we further found that the miR-99b-5p/nuclear mTOR (down/up) expression profile may serve as a promising prognostic biomarker in PCa, as well as in breast, colon, and lung cancers." (PMID 37370750, 2023). "Interestingly, the increased expression levels of USP5 protein had significantly promoted the progression of lung cancer cells by the mTOR signaling pathway and interacted with PARP1." (PMID 37060095, 2023). "Furthermore, in genetically engineered lung cancer mice an mTOR inhibitor combined with a PD-1 antibody decreased tumor growth, increased tumor-infiltrating T cells, and decreased regulatory T cells." (PMID 37370164, 2023). "To further examine whether any of the top 10 genes are correlated with ERBB and MTOR signaling pathways in lung cancer, we performed GSEA analysis using TCGA database." (PMID 37542131, 2023). "Furthermore, Platycodin-D, as a triterpene saponin isolated from Platycodon grandiflorum (Campanulaceae), obstructed PI3K/Akt/mTOR signaling pathways, thereby showing robust anti-lung cancer effects." (PMID 36984763, 2023). "Together, USP5 could promote the progression of lung cancer cells by mTOR signaling pathway and interacting with PARP1, indicating that USP5 may become a new target for lung cancer treatment." (PMID 37060095, 2023).
lung cancer (continued). "Furthermore, an inverse correlation between miR-99b-5p and mTOR expression levels was confirmed in other solid tumors including colon, breast, and lung cancers." (PMID 36077039, 2022). "Moreover, ENO1 was identified to promote the self-renewal and malignant phenotype of lung cancer stem cells by AMPK/mTOR pathway, and MPK/mTOR pathway is also the upstream initiator during the onset of autophagy mechanism." (PMID 35130884, 2022). "Moreover, GA increases LKB1 expression and suppresses mTOR signaling by activating AMPK in lung cancer." (PMID 35744960, 2022). "For example, in two studies of patients with metastatic renal cell carcinoma receiving anti-VEGF or mTOR-inhibitors and lung cancer receiving EGFR-TKI therapy, patients treated with statins concurrently had improved overall survival compared to statin non-users." (PMID 36017084, 2022). "Abnormal activation of the Akt/mTOR pathway is usually observed in lung cancer." (PMID 36311939, 2022). "In addition, other studies have shown that Huaier regulates lung cancer sensitivity to cisplatin via the mTOR pathway." (PMID 35470770, 2022). "Furthermore, we found that expression levels of these genes were associated with tumor metastasis; MAP2K1, mTOR, and TEAD1 were significantly overexpressed, while YAP and EGFR were under-expressed in metastasized lung cancer compared to primary tumors." (PMID 35655775, 2022). "Interestingly, we found that ARHGs with active copy number increase (e.g. MYC, EIF4EBP1, EGFR) and ARHGs with active copy number loss (e.g. ATG16L1, MTOR, ULK1) also showed high expression in lung cancer tissues." (PMID 35333893, 2022). "PGK1 could mediate the activation of the AKT/mTOR pathway, thus facilitating lung cancer metastasis." (PMID 35242214, 2022). "Since inhibition of the PI3K/AKT/mTOR pathway exhibits great antitumor effects against lung cancer, a variety of pan-PI3K inhibitors, selective PI3K inhibitors, AKT inhibitors, mTOR inhibitors, and dual PI3K-mTOR inhibitors have been developed in clinical trials." (PMID 36349192, 2022). "Furthermore, knockdown of SALL4 can restore cisplatin sensitivity in acquired resistant lung cancer cells via the AKT/mTOR signaling pathway, and the antineoplastic drug entinostat can target SALL4-positive lung cancer." (PMID 35216168, 2022). "A previous study found that ipomoea batatas polysaccharides could induce apoptotic cell death in lung cancer cells via Akt/mTOR-mediated autophagy activation and the autophagic degradation of Bcl-2, a antiapoptotic protein." (PMID 35624772, 2022). "Lung cancer cells down-regulate ferroptosis by up-regulating PI3K/AKT/mTOR." (PMID 36139919, 2022). "In addition, exosomes derived from cisplatin-resistant lung cancer cells have been found to use mTOR as a potential target to confer resistance to cisplatin on recipient cells in an exosomal miR-100-5p-dependent manner." (PMID 35465266, 2022). "Deregulation of mTOR signaling is prominent in a wide range of tumors, such as lung cancer." (PMID 36428613, 2022). "For example our lab studies found that miR-199a-3p and miR-199a-5p could directly co-target Rheb (Ras homolog enriched in the brain) in lung cancer, regulating the mTOR signaling pathway, inhibiting cell proliferation, migration, and promoting cell apoptosis." (PMID 35955652, 2022). "K-ras mutation, which is closely associated with lung cancer, requires PI3K and mTOR activation." (PMID 36286049, 2022). "IL-7 receptor complex could activate PI3K/Akt/mTOR signaling pathway in lung cancer cell line and leukemia transformation cell line." (PMID 35850640, 2022). "Recent reports have shown that Myh9 is crucial for maintaining stemness of lung cancer cells and promoting tumorigenesis via activating mTOR signals, suggesting Myh9 may exert a profound function on stem cells." (PMID 35740994, 2022).
lung cancer (continued). "These genes are enriched in mTOR and EIF2 signaling pathways, which the authors suggest might explain the activation of the mTOR pathway and EGFR-TKIs in lung cancers with EGFR mutations." (PMID 35205708, 2022). "It was reported that the mTOR pathway played an important role in follicular development, and that Baicalin could regulate the mTOR signaling pathway of human skin fibroblasts and lung cancer cells." (PMID 35300716, 2022). "Furthermore, IHC staining results have revealed that increased mTOR levels were detected in high-grade/advanced colon, breast, and lung cancer specimens." (PMID 36077039, 2022). "Lung cancer cells inhibit ferroptosis by activating PI3K/AKT/mTOR." (PMID 36139919, 2022). "mTOR, a pathway, is seen as dysregulated in many diseases including lung cancer." (PMID 35437508, 2022). "Next, we further investigated whether the miR-99b-5p can target/inhibit the AR/mTOR axis and promote cell apoptosis and/or enhance the docetaxel-induced cytotoxicity in colon, breast, and lung cancers." (PMID 36077039, 2022). "In conclusion, the present study screened 46 DEMs in GSE17681 and 1029 DEGs in GSE18842 and identified six hub genes related to lung cancer, including mTOR, NF1, CHD7, ETS1, IL-6, and COL1A1, which might be potential targets for lung cancer." (PMID 36211008, 2022). "Eriodictyol could inhibit the growth of lung cancer cell lines through induction of mitochondrial-mediated apoptosis, G2/M cell cycle arrest, and inhibition of mTOR/PI3K/Akt cascade signaling pathway." (PMID 35184647, 2022). "Moreover, paclitaxel induces ROS generation, DNA damage, and apoptosis in lung cancer cells by suppressing EGFR/PI3K/AKT/mTOR." (PMID 36139919, 2022). "On the other hand, concerning the relationship between mTOR and the expression of eukaryotic initiation factor-4E (eIF-4E) in lung cancer, there is evidence suggesting an involvement of the mTOR pathway in lung carcinogenesis via its binding to eIF-4E, acting as an oncogene in numerous studies." (PMID 36428613, 2022). "Consequently, co-targeting NOP56 and mTOR enhances apoptotic death of KRAS-mutant lung cancer cells in vitro and in vivo." (PMID 35039048, 2022). "ALA was shown to suppress lung cancer growth in mice models through mTOR autophagy inhibition." (PMID 35564468, 2022). "Furthermore, targeting c-Met with salvianolic acid A through the Akt/mTOR signaling pathway enhanced the sensitivity of lung cancer A549 cells to cisplatin." (PMID 35631459, 2022). "Oncogenic activation of AKT-mTOR pathway also promoted PD-L1 expression and the combinational treatment of mTOR inhibitor and PD-L1 antibody inhibited tumor growth in syngeneic and genetically engineered mouse models of lung cancer." (PMID 35884355, 2022). "In addition, six hub genes that were related to lung cancer were identified as hub genes, including mTOR, NF1, CHD7, ETS1, IL-6, and COL1A1." (PMID 36211008, 2022). "Taken together, the inhibition of the PI3K/Akt/mTOR pathway may offer a possible option for the improvement of lung cancer therapy." (PMID 36500361, 2022). "Notably, rapamycin showed little beneficial effects in NOP56 KD KRAS wild-type H1703 xenografts, which mirrors the in vitro data and reinforces the selective activity of co-targeting NOP56/mTOR in KRAS-mutant lung cancer." (PMID 35039048, 2022). "Therefore, targeting mTOR is an attractive and promising strategy for developing therapeutic agents for lung cancer." (PMID 35437508, 2022). "In addition, the EGFR tyrosine kinase inhibitor lapatinib regulated mTOR to promote ferroptosis in lung cancer cells." (PMID 35359830, 2022). "Interestingly, in HeLa and lung carcinoma cells A549, exposure to bafilomycin A1 or chloroquine impaired mTOR signaling as quantified by phosphorylation of S6RP, underlining the potential of these compounds to shape cellular pathways and metabolism." (PMID 36202792, 2022).
lung cancer (continued). "Moreover, knockdown of AKT expression, which leads to a loss of functional mTOR and p70S6K, results in MMP-2 and MMP-9 mRNA downregulation in lung cancer cells." (PMID 34279440, 2021). "The results suggest that genetically or pharmacologically activating Maf1 could improve radiotherapy for lung cancers or even other cancers, especially those that are resistant to rapamycin or deregulated in mTOR activity." (PMID 33640883, 2021). "Indeed, IL-7 activates PI3 K/Akt/mTOR signaling pathway via Beclin1 to regulate autophagy in lung cancer cells." (PMID 33773561, 2021). "In addition, we performed the Kaplan-Meier (KM) plotter to assess the prognostic significance of ERK, AKT, c-myc, mTOR and 4EBP1 in lung cancer patients." (PMID 34421360, 2021). "LncRNA MetaLnc9 promoted lung cancer metastasis through activation of AKT/mTOR signaling." (PMID 34234860, 2021). "A study on lung cancer observed that miR‐100‐5p could regulate mTOR and thus confer resistance against cisplatin treatment." (PMID 34469038, 2021). "In contrast, and more recently, a third study has observed the fact that targeting carbonic anhydrase IX may have an antitumor activity in lung cancer or improve antitumor activity of mTOR inhibitors." (PMID 33889306, 2021). "Thus, the ENO1-mediated activation of mTOR pathway would contribute to the stem cell maintenance of lung cancer." (PMID 33579362, 2021). "Our work revealed that miR-486-5p could hinder lung cancer tumorigenesis through inhibition and inactivation of the mTOR pathway by targeting RSK and p70S6K, and the miR-486-5p/RSK/mTORC1/p70S6K axis could be active." (PMID 34094949, 2021). "Furthermore, mTOR inhibitors reduced the proliferating potential of EGFR mutant drug-resistant lung cancer cells." (PMID 33996789, 2021). "Previous research has indicated that salvianolic acid A reverses cisplatin resistance by targeting c-met and attenuating the Akt–mTOR pathway in lung cancer and salvianolic-acid-B-attenuated cisplatin-induced cardiac injury and oxidative stress by modulating the Nrf2 signal pathway." (PMID 34679755, 2021). "Ongoing clinical trials of several drugs targeting PI3K/AKT/mTOR signaling in lung cancer." (PMID 34279440, 2021). "mTOR is a pathway found to be dysregulated in many disease states including cancer (lung cancer)." (PMID 34249899, 2021). "Additionally, the efficacy of PL in inducing apoptosis and autophagy in both in vitro and in vivo models of lung cancer was attributed to its role in suppressing the components of the PI3K/Akt/mTOR signaling pathway." (PMID 36046754, 2021). "As reported, fisetin could inhibit the proliferation and migration of human laryngeal cancer via ERK1/2 and AKT/NF-KB/mTOR signaling pathways and induce apoptosis in human lung cancer through the MAPK signaling pathway." (PMID 34257654, 2021). "Our findings indicate that the oversulfation of fucoidan promotes apoptosis of lung cancer cells and the mechanism may involve the Akt/mTOR/S6 pathway." (PMID 33921340, 2021). "Still, the use of mTOR inhibitor in combination with the PD-1 antibody in the mouse lung cancer model resulted in a significant inhibition of tumor growth, an increase in tumor-infiltrating lymphocytes (TILs) number, and a significant reduction in Tregs number." (PMID 34206937, 2021). "Twenty-four patients (58.5%) were switched to an mTOR-inhibitor after diagnosis of lung cancer." (PMID 34947875, 2021). "Additionally, the antitumor bioactivity of curcumin is achieved by inhibiting PI3K/Akt/mTOR pathway and inducing apoptosis and autophagy of human lung cancer A549 cells." (PMID 34512368, 2021). "In addition, PI3K/AKT, RTK, RAS/MAPK, TSC/mTOR pathways can also interact to promote the occurrence and development of lung cancer." (PMID 34497634, 2021). "Since autophagy occurs when mTOR is suppressed or AMPK is activated, we first tested whether eGSM inducing autophagy in lung carcinoma cells is associated with suppressing mTOR." (PMID 34758822, 2021).